FGF2 (fibroblast growth factor 2)
Diseases named in the same sentence as FGF2 in open-access papers (continued):
Sharing a sentence is not in itself a finding about the gene and the disease.
anemia (3 papers, 2012 to 2015). A reduction in the number of red blood cells, the amount of hemoglobin, and/or the volume of packed red blood cells. "Our new strategy not only promotes massive trabecular bone formation, but also leads to abrogation of the side effects associated with systemic FGF2 administration such as anemia and osteomalacia." (PMID 22629419, 2012). "We speculated that FGF2-associated extramedullary hematopoiesis and anemia is due to stem cell dysregulation." (PMID 22629419, 2012). "We reasoned that this might be because lethally irradiated animals are more susceptible to high-level FGF2-associated adverse effects like anemia, leading to severe sickness at ∼6 weeks after transplantation." (PMID 22629419, 2012). "The avoidance of anemia in the mice that received Sca1+ cells transduced with FGF2 driven by the β-globin promoter is likely due to attenuation of high-level serum FGF2-mediated stem cell mobilization observed in the SFFV-FGF2 animals." (PMID 22629419, 2012). "In our high SFFV-FGF2 group, we reproduced high-level FGF2-induced adverse effects such as anemia and osteomalacia." (PMID 22629419, 2012). "Together, this study resolved the apparent discrepancy and consolidated the conclusion that the β-globin promoter mediated confined FGF2 expression attenuates anemia and eliminates osteomalacia." (PMID 22629419, 2012). "To investigate the effects of FGF2 on anemia, we counted RBC in peripheral blood." (PMID 22629419, 2012). "The confined expression of FGF2 leads to a substantial increase in trabecular bone formation with no severe side effects like anemia and osteomalacia that are associated with systemic administration of FGF2." (PMID 22629419, 2012). "Systemic FGF2 administration induces side effects such as extramedullary hematopoiesis and anemia." (PMID 22629419, 2012). "Moreover, mice with high-level serum FGF2 developed anemia and osteomalacia." (PMID 22629419, 2012). "The confined FGF2 expression promotes considerable trabeculae bone formation in endosteum and does not yield anemia and osteomalacia." (PMID 22629419, 2012).
atrial fibrillation (3 papers, 2013 to 2024). A disorder characterized by an electrocardiographic finding of a supraventricular arrhythmia characterized by the replacement of consistent P waves by rapid oscillations or fibrillatory waves that vary in size, shape and timing and are accompanied by an irregular ventricular response. "Our previous study reveals a novel mechanism, by which cells overexpressing hi-FGF2 can induce mitochondria-associated apoptosis which is closely associated with HF.The level of hi-FGF2 can serve as a prognostic biomarker to predict the occurrence of HF in patients with atrial fibrillation (AF)." (PMID 38355415, 2024).
autoimmune disease (3 papers, 2017 to 2025). A disorder resulting from loss of function or tissue destruction of an organ or multiple organs, arising from humoral or cellular immune responses of the individual to their own tissue constituents. "Here we found that TGFβ expression was also up-regulated in the RA samples, suggesting that TGFβ also could induce FGF2 expression in infiltrated CD4+ T cells in the autoimmune disease." (PMID 28765647, 2017).
bladder (3 papers, 2017 to 2021). "These kidney pathologies are associated with basic fibroblast growth factor (FGF2), an important cytokine which facilitates renal matrix formation." (PMID 32410988, 2020).
cholesteatoma (3 papers, 2021). A pathologic process characterized by the proliferation of keratinizing squamous epithelium resulting in the accumulation of keratin and cells in the middle ear and/or mastoid. "Although middle ear cholesteatoma was mentioned in three experimental studies, there was no direct evidence that FGF2 induced cholesteatoma." (PMID 34306094, 2021).
colorectal tumor (3 papers, 2018 to 2024). "Furthermore, surface-associated FGF2 of fibroblasts binds to FGFR on colorectal tumor cells to induce tumor migration." (PMID 35618735, 2022). "Similar to our findings, FGF2 gene expression was shown in recent reports to be elevated in colorectal tumor tissue." (PMID 38954024, 2024).
cyst (3 papers, 2014 to 2025). A sac-like closed membranous structure that may be empty or contain fluid or amorphous material. "Therefore, Wnt3a, FGF-2, and Y-27632 are critical components for culturing cyst-enriched organoids." (PMID 37495742, 2023). "Neither control nor experimental mammary epithelia, including both Spry2Δ/Δ and Spry2-GOF epithelia, invaded toward beads pre-soaked in bovine serum albumin (BSA) or beads soaked in FGF2, which stimulate cyst formation (not shown), during the 72-hour time course." (PMID 24718286, 2014).
dementia (3 papers, 2018 to 2024). Loss of intellectual abilities interfering with an individual's social and occupational functions. "The expression levels of FGF-2 are elevated in a compensatory manner in dementia, whereas the artificial modulation of FGF-2 levels improves cognitive function in rodents." (PMID 37214403, 2023). "In recent decades, several researchers have observed opposing trends in the changes of FGF-2 in serum and brain tissue in dementia." (PMID 37214403, 2023). "In addition, FGF-2 has been shown to be a significant therapeutic target for certain anti-dementia medications, such as memantine." (PMID 37214403, 2023). "FGF-2 may also enhance the activation of M2-type MG and its phagocytosis of Aβ, thereby promoting neurogenesis in dementia." (PMID 37214403, 2023). "Reduced HGF/MET signaling contributes to synaptic pathology in the 5 × FAD mouse model of AD; while FGF2 gene transfer restores hippocampal functions in APP/PS1 mice; CRH (corticotropin-releasing hormone) has been proposed to play important roles in AD and other dementias." (PMID 39234102, 2024). "Therefore, despite ample evidence supporting the key role of FGF-2 in cognitive impairment and dementia, it still fails to become an independent clinical diagnosis or assessment indicator." (PMID 37214403, 2023).
esophageal adenocarcinoma (3 papers, 2008 to 2021). A malignant tumor with glandular differentiation arising predominantly from Barrett mucosa in the lower third of the esophagus. "In contrast, expression and translation of FGF-2 and GFG are tightly linked, and dysregulation of their expression is associated with poor clinical prognosis in esophageal adenocarcinoma." (PMID 18215310, 2008).
hematoma (3 papers, 2010 to 2021). A hematoma is a collection of blood from a vascular structure into an extravascular space. "Within 24 h after ICH, FGF-2 was ∼1.5-fold lower in the peri-hematoma region of four ICH patients, and the FGF-2 receptor, FGF2rb, was ∼2-fold lower in the striatum and cortex in the rat autologous blood-injection model." (PMID 26743212, 2016).
Hepatic steatosis (3 papers, 2022 to 2026). Steatosis is a term used to denote lipid accumulation within hepatocytes. "Additionally, in mouse models of fatty liver disease, FGF2 has been found to accelerate hepatocyte proliferation." (PMID 41602630, 2026).
Hepatitis (3 papers, 2008 to 2019). Inflammation of the liver. "Gremlin expression correlated with that of CK19 (r = 0.699, p = 0.003) and FGF2 (r = 0.75, p = 0.001) in hepatitis cases." (PMID 22839096, 2012). "FGF-2 correlated with each of grade (r = 0.603, p = 0.013), stage (r = 0.721, p = 0.002) and ductular reaction (r = 0.684, p = 0.004) in hepatitis cases." (PMID 22839096, 2012). "This explanation is further supported by our finding of a positive correlation between gremlin mRNA expression, FGF-2 and CK19 positivity in the hepatitis group." (PMID 22839096, 2012). "Proteins that uniquely distinguish HCC patients with low AFP from patients with hepatitis include IL1RN, IFNG, CDKN1A, RETN, CXCL14, and FGF2." (PMID 19578489, 2008). "FGF-2 expression was highest in HCCs and correlated with the grade (r = 0.6, p = 0.013), stage (0.72, p = 0.002), CK19 expression (r = 0.71, p = 002) and ductular reaction (0.68, p = 0.004) in hepatitis cases." (PMID 22839096, 2012). "Importantly, we also identified 8 proteins that significantly differentiate HCC patients with ‘normal’ levels of AFP (< 20 ng/ml) from hepatitis patients (p < 0.05) (IL1RN, IFNG, CDKN1A, RETN, CXCL14, CTNNB, FGF2, and SELL)." (PMID 19578489, 2008). "Gremlin expression did not correlate with the number of FGF-2 positive cells (r = 0.548, p = 0.191) or BMP-7 mRNA level (r = 0.051, p = 0.851) in the hepatitis group." (PMID 22839096, 2012).
Hodgkins lymphoma (3 papers, 2013 to 2022). A heterogeneous group of malignant lymphoid neoplasms of B-cell origin characterized histologically by the presence of Hodgkin and Reed-Sternberg (HRS) cells in the vast majority of cases. "FGF2 and SDC1 overexpression by circulating CD15+/CD 30+ cells is associated with poor outcome in Hodgkin Lymphoma." (PMID 23988031, 2013). "Recently, increasing evidence showed that FGF2 was important in the pathogenesis of haematological malignant tumours, such as chronic myeloid leukaemia (CML), chronic lymphoid leukaemia (CLL) and Hodgkin’s lymphoma." (PMID 36333298, 2022).
hypophosphatemia (3 papers, 2012 to 2020). Lower than normal levels of phosphates in the circulating blood. "Hyp mice had hypophosphatemia, reductions in 1,25(OH)2D levels, rickets/osteomalacia and elevated FGF2 expression in bone." (PMID 25089825, 2014). "However, this inference is not supported by our observation in the β-globin FGF2 animals, in which considerable trabecular bone formation was observed, while these animals manifest less severe hyperparathyroidism and hypophosphatemia compared to high SFFV-FGF2 animals." (PMID 22629419, 2012).
invasive breast carcinoma (3 papers, 2005 to 2023). A carcinoma that infiltrates the breast parenchyma. "In this study, FGF2 mRNA was downregulated in DCIS and invasive breast cancer tumors compared with normal breast tissues but upregulated in blood samples from DCIS and invasive breast cancer patients versus healthy individuals." (PMID 37445737, 2023). "FGF2 and S100P were overexpressed (p < 0.05) in both DCIS and invasive breast cancer patient blood samples." (PMID 37445737, 2023). "The correlation between EGFR expression and FGF2 and FGFBP1 gene expression levels in breast invasive carcinoma subtypes with purity adjustment was statistically significant in its positive correlation in all BRCA, except for BRCA-Her2." (PMID 36430763, 2022).
liver cirrhosis (3 papers, 2017 to 2025). "FGF2 levels were increased in hepatic stellate cell activation and liver cirrhosis." (PMID 30005700, 2018).
radiation-induced gastrointestinal syndrome (3 papers, 2015 to 2019). "Here, we evaluated the efficacy of fibroblast growth factor-2 (FGF2) in treating radiation-induced gastrointestinal syndrome (RIGS) incurred by lethal whole-body irradiation (WBI) when administered in conjunction with bone marrow transplantation (BMT)." (PMID 29515101, 2018).
rhinitis (3 papers, 2018 to 2022). An inflammation of the mucous membrane lining the nose, usually associated with nasal discharge. "Quantification analysis under the supervision of an experienced pathologist showed over a 7-fold increase of FGF-2+ signals in NPCs relative to NNTs or to rhinitis tissues." (PMID 35439170, 2022). "To further identify the cell type origin of FGF-2 in NPC tissues, we collected 3 NNTs, 10 rhinitis tissues, and 6 NPC tissues from patients receiving a nasopharyngoscopy test." (PMID 35439170, 2022). "Indeed, FGF2 and CD163 were significantly expressed in NPC tissues compared with rhinitis tissues." (PMID 35439170, 2022).
sarcoidosis (3 papers, 2019 to 2021). Sarcoidosis is a multisystemic disorder of unknown cause characterized by the formation of immune granulomas in involved organs. "The aim of this study was to assess the serum levels of those four proangiogenic and profibrotic markers VEGF, TGF-β1, FGF-2 and PDGF-AB in sarcoidosis and if there is an association of these serum markers with pulmonary impairment and quality of life." (PMID 33617593, 2021). "More specifically, we determined the concentrations of PDGF-AA, PDGF-BB, FGF-2, VEGF and M-CSF in whole lung homogenates from patients with PF-ILD of different aetiologies including IPF, SSc-ILD, other CTD-ILD, sarcoidosis and exposure related-ILD, and compared them to normal lung tissue." (PMID 31732480, 2019). "Concentrations of PDGF-AA, PDGF-BB, FGF-2, VEGF and M-CSF in whole lung homogenates from patients with PF-ILD of different aetiologies including IPF, systemic sclerosis (SSc) ILD, other CTD-ILD, sarcoidosis and exposure related-ILD were augmented as compared to healthy donor lungs." (PMID 31732480, 2019).
serous ovarian cancer (3 papers, 2014 to 2025). "Up-regulation of FGF2 (encoded by the FGF2 gene) was a pronounced predictor of paclitaxel resistance in serous ovarian cancer." (PMID 40507922, 2025). "In ovarian serous adenocarcinoma tissue, the subset of FGF-2-binding HS that is capable of activating FGF-2 was expressed predominantly by endothelial cells as well as the stroma." (PMID 37370735, 2023).
skin carcinoma (3 papers, 2012 to 2024). "Additionally, our prior mouse studies demonstrated that circulating FGF2 was associated with both visceral adiposity and ultraviolet radiation-induced skin cancer and an epidemiological study demonstrated that circulating FGF2 levels in humans are associated with overall adipose tissue mass." (PMID 34685650, 2021). "For skin carcinoma, cells from the dermis, fibroblasts and endothelial cells, can be the main sources of secreted FGF2." (PMID 22732006, 2012).
status epilepticus (3 papers, 2010 to 2024). Status epilepticus is defined as a continuous seizure lasting more than 30 min, or two or more seizures without full recovery of consciousness between any of them. "In a study, BDNF and FGF-2 induced a rapid attenuation of astrocytosis and microgliosis and prevented the IL-1β overexpression that is typical of the post-status epilepticus period." (PMID 38673746, 2024). "Similar immunoinhibitory effects attenuating astrocytosis, microcytosis, and cytokine production are observed via BDNF supplementation, together with fibroblast growth factor-2 (FGF-2) in a model of status epilepticus, leading to a significant reduction in seizure frequency." (PMID 35955546, 2022). "Specifically, the delivery of FGF-2 and BDNF in the rat hippocampus after pilocarpine-induced status epilepticus reduced various markers of inflammation including astrocytosis, microgliosis, and IL-1β expression." (PMID 38673746, 2024). "Thus, we used a Herpes-based vector to supplement FGF-2 and BDNF in rat hippocampus after pilocarpine-induced status epilepticus that established an epileptogenic lesion." (PMID 21087489, 2010).
tendinitis (3 papers, 2018 to 2025). Inflammation of a tendon, usually resulting from an overuse injury. "Plasmid DNA encoding VEGF164 and FGF2 is a novel treatment of naturally occurring tendinitis and desmitis in horses." (PMID 34777022, 2021). "Ultrasonographic results of the SDFT tendinitis horse before and after treatment with plasmid DNA encoding VEGF164 and FGF2 genes." (PMID 30233367, 2018). "In one clinical study, the plasmid DNA encoding two therapeutic species‐specific growth factors VEGF164 and fibroblast growth factor 2 (FGF2), were successfully used to treat SDF tendinitis and desmitis of suspensory ligament branch." (PMID 39267222, 2025).
Urethral stricture (3 papers, 2022 to 2025). Narrowing of the urethra associated with inflammation or scar tissue. "We also found that urinary tract diseases significantly increased FGF-2 concentrations by 26% (0.56 pg/mL)." (PMID 40943671, 2025). "We found that urinary tract diseases significantly impacted FGF-2, explaining 26% of the variation and increasing its concentration by 0.56 pg/mL." (PMID 40943671, 2025).
vitamin D deficiency (3 papers, 2014 to 2022). A nutritional condition produced by a deficiency of VITAMIN D in the diet, insufficient production of vitamin D in the skin, inadequate absorption of vitamin D from the diet, or abnormal conversion of vitamin D to its bioactive metabolites. "Vitamin D deficiency in aging rats was also associated with decreased mRNA expression of bone morphogenetic protein 4 (Bmp4) and fibroblast growth factor-2 (Fgf-2), markers that play a role in satellite cell proliferation." (PMID 36364820, 2022). "Vitamin D deficiency in aged rats was also associated with decreased Bmp4 and Fgf2 mRNA expression." (PMID 36364820, 2022). "Here we speculate that vitamin D deficiency could result in a poor recruitment of SC into their proliferating state, due at least in part to a down-regulation of Fgf2, making them ready for programmed differentiation, as Bmp-4 is down-regulated." (PMID 25317198, 2014).
abdominal aortic aneurysm (2 papers, 2024 to 2025). Enlargement and ballooning of the vessel that supplies arterial blood to the abdomen, pelvis and legs. "Expression of nudix hydrolase 6 (NUDT6), an antisense transcript targeting fibroblast growth factor 2 (FGF2), increases in tissue samples from patients with abdominal aortic aneurysm and carotid artery disease." (PMID 40224357, 2025). "In vivo targeting of Nudt6 (which is an antisense transcript of fibroblast growth factor 2; FGF2) with ASO, using murine and porcine models of carotid artery disease and abdominal aortic aneurysm, showed limited disease progression." (PMID 39273193, 2024).
acute lymphoblastic leukemia (2 papers, 2021 to 2024). Leukemia with an acute onset, characterized by the presence of lymphoblasts in the bone marrow and the peripheral blood. "Additionally, activation of FGFR by FGF2 stimulation was involved in prednisolone resistance in B cell precursor acute lymphoblastic leukemia cells." (PMID 33406639, 2021).
adenoma (2 papers, 2010 to 2017). A neoplasm arising from the epithelium. "In lung preneoplasias and adenomas of tobacco carcinogen exposed mice, the anti-estrogen fulvestrant and/or the aromatase inhibitor anastrozole blocked FGF2 and FGF9 secretion, and reduced expression of the stem cell markers SOX2 and nanog." (PMID 28445992, 2017). "After treatment with fulvestrant, anastrozole, or the combination, both preneoplasias and adenomas showed reduced staining for FGF2, FGF9, and Nanog." (PMID 28445992, 2017).
alopecia areata (2 papers, 2024). Loss of scalp and body hair involving microscopically inflammatory patchy areas. "In this line of investigation, the authors also used liposome-incorporated basic fibroblast growth factor (FGF-2) to prevent hair loss in patients with alopecia areata." (PMID 38542108, 2024).
ameloblastoma (2 papers, 2013 to 2021). The most common odontogenic tumor, arising from the epithelial component of the embryonic tooth and usually affecting the molar-ramus region of the mandible or maxilla. "The expression of FGF1, FGF2, FGFR2 and FGFR3 in ameloblastoma was previously reported and it was concluded that FGF1 and FGF2 may contribute to the growth and development of ameloblastoma mediated by their receptors." (PMID 24002438, 2013).
amyloid (2 papers, 2014 to 2024). "Taken together, our findings suggest that the FGF2 secretion induced by amyloid pathology is sufficient to promote FGFR3-mediated tau uptake in neurons." (PMID 38951140, 2024). "Unlike changes in FGF2, FGFR3 levels were not altered by Aβ treatment or amyloid pathology." (PMID 38951140, 2024).
androgenetic alopecia (2 papers, 2025). "For instance, Gentile and Garcovich reported that adding dihydrotestosterone (DHT) to DPCs from patients with androgenic alopecia decreases the expression of FGF7 within cells while increasing the secretion of both FGF7 and FGF2." (PMID 40867641, 2025). "FGF2, commonly known as basic FGF (bFGF), demonstrated promising results in a Phase I clinical trial that evaluated the effects of intradermal injections in patients with androgenetic alopecia." (PMID 40867641, 2025).